NDRG2 (NDRG family member 2)
Diseases named in the same sentence as NDRG2 in open-access papers (continued):
Sharing a sentence is not in itself a finding about the gene and the disease.
glioblastoma (12 papers, 2007 to 2026). The most malignant astrocytic tumor (WHO grade IV). "The main molecular mechanism responsible for the frequent transcriptional downregulation of NDRG2 expression observed in primary glioblastoma appears to be aberrant promoter methylation." (PMID 41596413, 2026). "Transcriptional downregulation of the NDRG2 gene on chromosome 14 has been observed in primary glioblastoma patients." (PMID 35327982, 2022). "Several studies have suggested that the NDRG2 mRNA is down-regulated or undetectable in a number of human primary cancers, such as squamous cell carcinoma, pancreatic cancer, glioblastoma, and cancer cell-lines." (PMID 19257893, 2009). "Forced NDRG2 overexpression in a human glioblastoma cell-line markedly inhibited cell proliferation." (PMID 17935612, 2007). "Semiquantitative RT-PCR was used to demonstrate that NDRG2 expression levels were reduced in squamous cell carcinoma, pancreatic cancer and glioblastoma compared to normal tissue." (PMID 17935612, 2007). "Glioblastomas show significant alterations in NDRG2 expression." (PMID 41596413, 2026). "It was shown that NDRG2 reduce tumor cell proliferation in glioblastomas." (PMID 28390436, 2017). "We found that the expression of NDRG2 was significantly reduced in human glioblastoma tissues." (PMID 18940011, 2008). "We also found that expression of NDRG2 in human glioblastoma tissues was significantly lower than in normal tissue and demonstrated that Myc repressed human NDRG2 through a Miz-1-dependent interaction with the core promoter of NDRG2." (PMID 18940011, 2008). "While it was found that NDRG2 and NDRG4 had opposing protein expression patterns when comparing normal brain tissue to glioblastoma tissue, suggesting the opposite function of NDRG4 to NDRG2, although NDRG4 is most similar to NDRG2 within the NDRG family." (PMID 25749388, 2015).
lung carcinoma (12 papers, 2013 to 2025). "In the present study, it has reported for the first time that NDRG2 expression was deficient in human lung cancer compared with normal lung tissues, and NDRG2 mRNA level increased with tumor differentiation grade but decreased with tumor advancement both in squamous carcinoma and adenocarcinoma." (PMID 23307246, 2013). "Salvianolic acid B (Sal B) can induce oxidative stress and inhibit the growth and metastasis of lung cancer A549 cells through the NDRG2/PTEN signaling pathway." (PMID 40223054, 2025). "In a separate study, overexpression NDRG2 protein via a survivin promoter suppressed the viability and invasiveness of lung cancer cells." (PMID 40223054, 2025). "This latter effect results in the proteasomal degradation of NDRG2 to potentially promote lung cancer tumorigenesis." (PMID 40378957, 2025). "The expression of the NDRG2 gene is downregulated in human lung cancer tissues and is considered a favorable prognostic indicator for lung cancer." (PMID 40223054, 2025). "In a human lung cancer cell line, A594, mRNA and protein of NDRG2 were upregulated under hypoxic conditions." (PMID 34685629, 2021). "In this report, we present evidence that NDRG2 is also modified by SUMOylation catalyzed by RING finger protein 4 (RNF4) and that SUMOylation is required for NDRG2 regulated tumorigenesis in lung carcinoma cells." (PMID 27072586, 2016). "In summary, our data reveal an unexpected regulatory mechanism in which SUMOylation increases the ability of NDRG2 to inhibit lung cancer tumorigenesis, and RNF4 targets NDRG2 to proteasomal degradation by stimulating its SUMOylation." (PMID 27072586, 2016). "CpG island methylation, which changes NDRG2 gene expression patterns, has been observed in breast, colon, and lung cancer cells." (PMID 25061501, 2014). "The goal of this study was to determine the expression pattern of NDRG2 in human lung cancer and its correlation with prognosis." (PMID 23307246, 2013). "The present study was conducted to explore the function of NDRG2 in the process of lung cancer development." (PMID 23307246, 2013). "Both RT-PCR and Western blots demonstrated that NDRG2 mRNA and protein levels were lower in lung cancer compared to the adjacent normal tissue from the same individual, and NDRG2 level was negatively correlated with UICC stage." (PMID 23307246, 2013). "The expression level of NDRG2 was closely related to the prognosis of patients with human lung cancer." (PMID 23307246, 2013). "In summary, our data showed for the first time that NDRG2 expression was decreased in human lung cancer, and the NDRG2 level was positively correlated with tumor differentiation grade, while negatively correlated with UICC stage." (PMID 23307246, 2013). "Meanwhile, COX regression analysis indicated that low expression of NDRG2, ≥pT3, pM1, ≥pN1 and vascular invasion were independent, poor prognostic factors of lung cancer patients." (PMID 23307246, 2013). "Results showed that the expression level of NDRG2 was decreased in human lung cancer tissues, and NDRG2 was positively correlated with depth of invasion (P = 0.038), vascular invasion (P = 0.036), tumor grade (P = 0.039), and tumor size (P = 0.026)." (PMID 23307246, 2013). "Immunohistochemistry, RT-PCR and western blot were used to explore the expression of NDRG2 in 185 human lung cancer patients." (PMID 23307246, 2013).
lung carcinoma (continued). "By using immunohistochemistry, RT-PCR, and western blot, this study detected and compared the expression level of NDRG2 in 185 lung cancer tissues and normal controls and analyzed the relationship between NDRG2 level and clinical pathological information." (PMID 23307246, 2013). "Decreased N-MYC downstream-regulated gene 2 (NDRG2) is important for the tumorigenesis of lung cancer and may be considered a valuable prognostic marker in lung cancer." (PMID 34112123, 2021). "Additionally, survival time of lung cancer patients with high expression of NDRG2 was longer than those with low expression during the 5-year follow-up period (P = 0.001)." (PMID 23307246, 2013). "NDRG2 could be considered as a potentially valuable prognostic indicator in patients with lung cancer." (PMID 23307246, 2013). "The actions of NDRG2 in lung cancer remain unclear, however." (PMID 27072586, 2016). "However, the possible role of NDRG2 in lung cancer remains to be elucidated." (PMID 23307246, 2013). "NDRG2 might serve as a novel prognostic marker in human lung cancer." (PMID 23307246, 2013). "In the present study, we confirmed that NDRG2 can be modified by SUMO1 in lung adenocarcinoma cells and that NDRG2 SUMOylation increases the protein's ability to inhibit lung cancer tumorigenesis." (PMID 27072586, 2016). "Our data illustrate a new approach to correlating the expression patterns of NDRG2, RNF4 and SUMO machinery in lung cancer." (PMID 27072586, 2016). "The overall survival analysis using the Kaplan–Meier method revealed that the prognosis of lung cancer patients with high or moderate NDRG2 expression was significantly better than those with no or weak NDRG2 expression, and moderate expression was better than high expression (P = 0.001)." (PMID 23307246, 2013).
gastric cancer (10 papers, 2008 to 2020). A primary or metastatic malignant neoplasm involving the stomach. "Here, we analyzed H. pylori infection and aberrant Ndrg2 methylation in gastric cancer, the association between H. pylori infection and Ndrg2 methylation and its possible mechanism." (PMID 25823664, 2015). "Ndrg2 promoter methylation was associated with H. pylori infection and worse prognosis of gastric cancer patients, which is an independent prognostic factor for the disease-free survival (DFS)." (PMID 25823664, 2015). "Over-expression of NDRG2 caused an inhibition of cell proliferation and increased apoptosis in gastric cancer, through Fas-mediated cell death." (PMID 18940011, 2008). "Together, these data indicate that Ndrg2 might have a clinical significance as a marker associated with negative regulation of tumor progression in gastric cancer." (PMID 25823664, 2015). "The loss of Ndrg2 expression could have been caused by a number of genetic or epigenetic events during gastric cancer progression." (PMID 25823664, 2015). "Immunohistochemical analysis of Ndrg2 protein expression in gastric cancer indicated that Ndrg2 expression loss is closely correlated with tumor size, histological differentiation, venous invasion, lymphatic involvement, invasive depth, lymph node metastasis and clinical stage (all P<0.05)." (PMID 25823664, 2015). "Therefore, we conclude that methylation-induced promoter inactivation might be the major cause of the frequent loss of Ndrg2 expression in gastric cancer." (PMID 25823664, 2015). "Immunohistochemistry was used to detect the expression of HIF-1α, NDRG2, E-cadherin, Snail and Twist in normal gastric tissues, gastric cancer tissues and lymph node metastasis." (PMID 33817155, 2019). "Silencing NDRG2 expression in gastric cancer cell line SNU-620 has been shown to promote the proliferation of gastric cancer cells." (PMID 33817155, 2019). "The differences in the expression of NDRG2 among normal gastric tissues, gastric cancer tissues, and lymph node metastasis tissues were statistically significant (X2=30.179, P<0.001)." (PMID 33817155, 2019). "There was a significant difference in expression of NDRG2 between gastric cancer tissues and lymph node metastasis tissues (Fisher, P=0.047)." (PMID 33817155, 2019). "NDRG2 phosphorylation affects NDRG2 protein activity and is induced by HT in an Akt-dependent manner in gastric cancer cells." (PMID 26506239, 2016). "Next, we evaluated Ndrg2 mRNA expression level in 292 primary gastric cancer tissues, as well as their corresponding para-cancerous histological normal tissue (PCHNT) specimens and 125 non-cancer volunteers." (PMID 25823664, 2015). "In the present study, we showed that the CpG sites in the Ndrg2 promoter were mostly hypermethylated in gastric cancer cell lines and primary tumors, whereas those in normal gastric tissues remained unmethylated." (PMID 25823664, 2015). "We also evaluated the correlation between Ndrg2 methylation and H. pylori infection in gastric cancer." (PMID 25823664, 2015). "The methylation of Ndrg2 was found in 54.0 % (47/87) of primary gastric cancer specimens and related to gastric cancer progression." (PMID 25823664, 2015). "5-Aza-CdR treatment significantly restored Ndrg2 expression in Ndrg2 silenced gastric cancer cell line HGC-27 cells." (PMID 25823664, 2015). "We found that H. pylori silenced Ndrg2 by activating the NF-κB pathway and up-regulating DNMT3b, promoting gastric cancer progression." (PMID 25823664, 2015). "Our results suggest that the mechanism that accounts for Ndrg2 methylation in H. pylori-related gastric cancer is elevated DNMT activity secondary to the up-regulation of DNMT3b." (PMID 25823664, 2015). "To investigate the candidacy of Ndrg2 as a suppressor in gastric progression, we initially characterized the expression status of Ndrg2 transcript in five gastric cancer cell lines." (PMID 25823664, 2015).
gastric cancer (continued). "We found that Ndrg2 promoter was frequently hypermethylated in gastric cancer cell lines and in 292 gastric tumor tissues." (PMID 25823664, 2015). "In present study, we investigated the biological function and clinical significance Ndrg2 in gastric cancer progression." (PMID 25823664, 2015). "RT-PCR analysis showed that Ndrg2 mRNA expression is repressed in 4 of 5 gastric cancer cell lines examined and in human gastric cancer samples." (PMID 25823664, 2015). "In an early study, it was shown inhibition of NDRG2 resulted in slightly increased proliferation and cisplatin resistance as well as decreased Fas expression and Fas-mediated cell death in gastric cancer cells." (PMID 22920753, 2012). "Therefore, the question to be asked is what is the association of gastric cancer metastasis with HIF-1α and NDRG2?" (PMID 33817155, 2019). "This suggests that NDRG2 can inhibit the proliferation of gastric cancer cells." (PMID 33817155, 2019). "We also found that the loss of Ndrg2 expression in primary gastric cancer is carried on to the secondary tumors formed during metastatic progression, likely due to inheritance of the promoter hypermethylation pattern at Ndrg2 locus (data no shown)." (PMID 25823664, 2015). "We found that Ndrg2 was frequently down-regulated in gastric cancer and provided evidence suggesting that this observation can have significant implications in the negative regulation of gastric cancer progression." (PMID 25823664, 2015). "Ndrg2 contains a CpG island in its promoter region and DNA hypermethylation has been reported in pancreatic cancer, glioblastoma, adrenocortical carcinomas, breast cancer, colorectal cancer, oral squamous-cell carcinoma, meningioma, liver, and gastric cancer." (PMID 25823664, 2015). "Our results provided the evidence that Ndrg2 could contribute to the negative regulation of gastric cancer progression." (PMID 25823664, 2015). "To understand the molecular mechanism of the predominant transcriptional repression of Ndrg2 in gastric cancer cells, we investigated the DNA methylation status of a CpG island encompassing the proximal promoter of Ndrg2 using a real-time methylation-specific PCR (MSP)." (PMID 25823664, 2015). "Our results suggest that H. pylori, as an initiator of the inflammatory tumor microenvironment, might promote the tumorigenesis and progression of gastric cancer through the regulation of epigenetic tumor suppressor genes silencing such as Ndrg2 methylation." (PMID 25823664, 2015). "Further investigations on the molecular mechanism of Ndrg2 methylation in gastric cancer mediated by H. pylori infection may offer a novel approach for the prevention and treatment of gastric cancer." (PMID 25823664, 2015). "Present studies suggest that Ndrg2 might be a novel candidate suppressor of tumor progression in gastric cancer." (PMID 25823664, 2015). "NDRG2 also functions as a prognostic marker in gastric cancer." (PMID 25061501, 2014). "The discrepancy of NDRG2 in cisplatin resistance in cervical cancer and gastric cancer cells may due to tissue specificity." (PMID 22920753, 2012). "Also studies of NDRG2 gene expression in gastric carcinoma revealed decreased expression levels of the gene in some of the patients." (PMID 20804549, 2010). "In summary, these data indicate that in addition to a majority of clinical characteristics that have been shown to affect prognosis of gastric cancer patients, the methylation level of Ndrg2 might serve as an independent marker to predict the DFS of the patients." (PMID 25823664, 2015). "Moreover, the authors suggested that studies of NDRG2 gene expression could be used as a prognostic factor for the survival rate of patients with gastric carcinoma." (PMID 20804549, 2010). "NDRG2 may be involved in tumor progression and overall survival of gastric cancer patients." (PMID 18940011, 2008).
gastric cancer (continued). "In gastric cancer tissues, there was a statistically significant different between the expression of HIF-1α and Snail, HIF-1α and Twist, NDRG2 and Snail, and NDRG2 and Twist." (PMID 33817155, 2019). "In this study, the expression of HIF-1α, NDRG2 and EMT-related proteins, including E-cadherin, Snail and Twist were evaluated in normal gastric tissues, gastric cancer tissues and lymph node metastasis tissues." (PMID 33817155, 2019). "By increasing the phosphorylation of NDRG2, HT can also exert anti-tumor effects on MKN28 gastric cancer cells." (PMID 26506239, 2016). "This study aims to investigate the differences in the expression of hypoxia-inducible factor-1α (HIF-1α), N-myc downstream-regulated gene 2 (NDRG2) and epithelial mesenchymal transition (EMT)-related proteins in normal gastric tissues, gastric cancer tissues and lymph node metastasis." (PMID 33817155, 2019). "At present, the correlation between the expression of HIF-1α and NDRG2 in gastric cancer and lymph node metastasis tissues has not been reported." (PMID 33817155, 2019). "The methylation of NDRG2 is higher in primary gastric cancer specimens than in corresponding nonmalignant gastric tissues, and this pattern is also observed in OSCC." (PMID 26506239, 2016). "Our data showed that Ndrg2 expression was significantly reduced in the majority of gastric cancers compared with adjacent non-tumor tissues, which is similar to others." (PMID 25823664, 2015). "In this study, we investigated the expression level and methylation status of Ndrg2 in 292 gastric cancer and matched noncancerous tissues, and we evaluated the clinical significance of abnormal Ndrg2 methylation in gastric cancer." (PMID 25823664, 2015). "In gastric cancer tissues, the difference in the expression between HIF-1α and NDRG2 was not statistically significant, (Fisher, P=1.000)." (PMID 33817155, 2019).
melanoma (10 papers, 2010 to 2025). A malignant, usually aggressive tumor composed of atypical, neoplastic melanocytes. "Overexpression of NDRG2 in tumor suppressed the intratumoral and peritumoral angiogenesis in melanoma." (PMID 34013046, 2021). "Overexpression of NDRG2 in tumors suppressed the intratumoral and peritumoral angiogenesis in melanoma." (PMID 34013046, 2021). "Our qPCR results showed significant down-regulation of PAX9, NDRG2, and ACVR2a in melanoma compared with normal, and the relative expression of the respective miRNA–mRNA pairs showed significant negative correlation." (PMID 31569419, 2019). "We found, PAX9 and NDRG2, which were down-regulated in human and mouse melanoma, also were down-regulated in COM." (PMID 31569419, 2019). "In fibrosarcoma and murine melanoma, NDRG2 expression significantly suppresses tumor invasion by inhibiting MMP activity, which is regulated by NF-κB signaling." (PMID 26506239, 2016). "Finally, down-regulation of the NDRG2 (NDRG family member 2) gene was reported to inhibit the metastatic potential of melanoma cells in vitro and in vivo." (PMID 22984562, 2012). "Interestingly, when 5AzaCdR treatment was given in combination to TSA, a significant up-regulation of NDRG2 expression was found in Mel-2 metastatic melanoma cells." (PMID 22984562, 2012). "Another study demonstrated that NDRG2 expression is significantly reduced in HT1080 human fibrosarcoma and B16F10 murine melanoma cell lines, which are known for their enhanced metastatic potential." (PMID 40378957, 2025). "Kim and colleagues demonstrated that NDRG2 expression significantly suppressed tumor invasion by inhibiting MMP activities, an angiogenic switch during carcinogenesis, which is regulated through the NF-κB signaling pathway in melanoma." (PMID 40378957, 2025).